FOXO3 (forkhead box O3)
Diseases named in the same sentence as FOXO3 in open-access papers (continued):
Sharing a sentence is not in itself a finding about the gene and the disease.
tumor (continued). "However, circ-Foxo3 exerts a different role in GC, PCa and GBM—it promotes tumor progression via the circ-Foxo3/miR-143-3p/mRNA USP44, circ-Foxo3/miR-29a-3p/mRNA SLC25A15, and circ-Foxo3/miR-138-5p/432-5p/mRNA NFAT5 axes." (PMID 33833780, 2021). "Notably, overexpression of FOXO3 in the METTL3‐knockdown Hepa1‐6 cells rescued the sorafenib sensitivity effect, as reflected by the significant decrease of tumor size and tumor weight comparing to the groups treated with solvents." (PMID 32368828, 2020). "FOXO3, a potential SIRT3 target, belongs to the forkhead box class O transcription factor family which can regulate various cellular and physiological processes, such as metabolism, development, and tumor suppression." (PMID 33298860, 2020). "As reported in our lifespan studies, haploinsufficiency of the Foxo1 or Foxo3 gene did not affect the lifespans and incidences of neoplasms at death in the AL groups." (PMID 32630045, 2020). "Moreover, TNF-α, IL-6, and several typical differentially expressed phosphorylated proteins (such as p-CCNB1, p-FOXO3, and p-STAT3) in tumor tissues, tumor cell viability, and cell cycle arrest assay in vitro further verify the results of IPA." (PMID 33344655, 2020). "Further evidence that IR-780 induced a more pronounced effector phenotype was attained by the assessment of multiple CTL effector markers through real-time qPCR of the whole tumor mRNA, demonstrating increased expression of IFN-γ, TNF-α, Granzyme B, EOMES, Perforin, BLIMP-1, FOXO3, and CXCL10." (PMID 31781498, 2019). "Although circ‐Foxo3 acts as a tumor suppressor, like its host gene Foxo3, the levels of the circular RNA are not correlated with the level of the corresponding linear mRNA." (PMID 30719845, 2019). "Interestingly, we found increased expression of pFOXO1 (transcriptionally inactive) and decreased expression of FOXO3 in in-vitro, in-vivo and ex-vivo samples, thus supporting the findings that FOXO family members can promote tumor progression." (PMID 30413788, 2018). "In the analysis of 103 paired tumor and adjacent nontumor tissue samples, we found that FOXO3 expression was significantly lower in tumor tissues than in adjacent nontumor tissues." (PMID 30514328, 2018). "Akt-phosphorylated FoxO3(Ser253) was not affected by tumor implantation as well as by (+)-JQ1 treatment." (PMID 29167426, 2017). "Trib3 was shown to enhance the tumorigenicity of a variety of tumor cell lines and xenografts via a mechanism that involved dysregulation of AKT phosphorylation by the mTORC2 complex and subsequent inactivation of the transcription factor FOXO3." (PMID 27191957, 2016). "Frank tumours were preceded by elevated macrophage numbers in FoxO3−/− vavP-MYC10 mice but, surprisingly, pre-B-cell numbers were relatively normal in healthy young FoxO3−/−Eμ-myc mice." (PMID 26764572, 2016). "The data suggested that the mediation of Foxo3 and TRIM31 by miR-551b was occurring in vivo and might play a key role in the observed impacts of miR-551b on tumor growth." (PMID 27743201, 2016). "Therefore, concerning FOXO3-expression levels, T32-phosphorylation and subcellular localization, drug-treated STA-NB15 cells mimic the phenotype of neuroblasts in tumor tissue from stage IV patients." (PMID 27769056, 2016). "In parallel, presumably due to selective pressure, also the number of FOXO3-negative tumor cells increased during therapy, suggesting increased heterogeneity of the residual tumor tissue after 4OHT-treatment, similar to stage IV NB tumors." (PMID 27769056, 2016). "In carcinogenesis, FOXO3 and FOXO1 both suppress tumor growth." (PMID 24864265, 2014).
tumor (continued). "This suggests that FoxO3 transactivation could be induced by the RASSF1A-MST1 pathway and function as a tumor suppressor system in response to specific oncogenic signals, such as BRAFV600E." (PMID 21249150, 2011). "Overexpression of SIRT1 enhanced FOXO3 deacetylation and activity, promoting BNIP3 transcription and PINK1/Parkin-mediated mitophagy, which in turn promoted cell proliferation, migration, invasion, and inhibited apoptosis in vitro, as well as increased tumor growth and hormone resistance in vivo." (PMID 39266959, 2024). "In addition, FOXO3-overexpressing cells showed lower TIF and tumor volumes in vivo." (PMID 34795388, 2022). "Among the anti-tumor effects of regorafenib, this TKI could modulate the autophagy pathway to counteract tumor cell survival, but the effect of regorafenib on FOXO3 and autophagy regulation in sorafenib-resistant HCC has not been studied yet." (PMID 34769197, 2021). "The full-text of 117 articles was checked for eligibility, finding 69 articles without patients (only cell or animal models), one without English full-text, 10 without HCC patients and 32 without FOXO3-related tumor pathogenesis, survival or clinicopathological features evaluation." (PMID 34771514, 2021). "Furthermore, regorafenib, one of the main second-line drugs administered when sorafenib fails, demonstrated for the first time that its anti-tumor action in sorafenib-refractory HCC is mediated, at least in part, through FOXO3 downregulation and autophagy abolition." (PMID 34769197, 2021). "To understand the extent to which the FOXO3 NSC signatures correlate with the GBM transcriptional networks we identified, we calculated an ssGSEA score for the FOXO3-activated and -repressed NSC signatures across the 169 TCGA tumor samples used in our initial analysis." (PMID 36303712, 2021). "However, a later study by the same research group has shown that SIRT1 and SIRT2 mediate deacetylation of FOXO3 to promote FOXO3 ubiquitination and degradation in Skp2-dependent manner, implying that acetylation increases FOXO stability and enhances its tumour-suppressive function." (PMID 32372224, 2020). "Moreover, blockade of IL-4 resulted in overexpression of pro-inflammatory cytokines (CXCL10, IL-1β, IL-15, IL-10 and IL-6) and lower expression of immunosuppressive molecules (Foxo3, IDO1 and PD-L1) as compared to cryo-thermal eosinophils + tumour-bearing DCs group." (PMID 31519961, 2019). "Moreover, tumour-bearing DCs co-cultured with cryo-thermal eosinophils resulted in a significant down-regulation of immunosuppressive molecules, HO-1, STAT3, Foxo3, IDO2, VEGFR2 and PD-L1 as compared to tumour-bearing DCs co-cultured with tumour-bearing eosinophils." (PMID 31519961, 2019). "In addition, FOXO3 regulates the differentiation of naïve regulatory T-cells via its transcriptional target FOXP3, which limits the cytotoxic anti-cancer T-cell response by immune-suppressive regulatory T-cells that infiltrate tumor tissue." (PMID 31789593, 2019). "Among other processes that can be associated to an AMPK-dependent positive modulation of Forkhead box O3 (FOXO3) and a negative modulation of mTOR/AKT, MET may specifically act on tumor-initiating GSC cells." (PMID 31214505, 2019). "The combined data support the model that ROS-driven FOXO3 activation enhances the cytotoxic effect of MG-2477 by modulating the regulation of NOXA, Survivin and possibly other death regulators, which triggers additional death pathways and eventually drives the tumor cell into cell death." (PMID 28415610, 2017). "Therefore, reduced tumor p27 expression is not due to a reversal of the effect of miR-106a~363 on Foxo3 and Foxo4 transcription." (PMID 28881594, 2017).
tumor (continued). "However, residual NB cells may tolerate or even benefit from FOXO3 activation in presence of hyperactive PKB, which will contribute to the development of more aggressive tumor cells and disease relapse." (PMID 27769056, 2016). "They identified several candidate tumor-suppressor genes that were down-regulated in these regions and their subsequent investigations suggested that two of these suppressor genes, PRDM1 and FOXO3, were considered playing an important role in the pathogenesis of NK-cell neoplasms." (PMID 26141723, 2015). "Recently, we identified a functional connection between FOXO3 and the transcriptional activation of the tumour suppressor gene Liver Kinase B1 (LKB1), which is known to block cell cycle progression and which is frequently lost in many forms of human tumours, including cervical cancer." (PMID 22848740, 2012). "Interestingly, FOXO3 and AIM2 showed opposite correlations with macrophages, which may be related to the lack of detailed typing of macrophages (M1 macrophages behaved as tumor suppressors, whereas M2 macrophages behaved as tumor promoters)." (PMID 35847844, 2022). "Thus, the exact crosstalk between FOXO3, autophagy, and sorafenib resistance in HCC remains fully unclear and needs to be further and consistently studied, especially using adequate sorafenib-resistant HCC in vitro models and exploring tumor cell response under normal oxygen conditions." (PMID 34769197, 2021). "This suggests that the downregulation of FOXO3 independent of CBX2 could drive tumor progression." (PMID 30478317, 2018). "However, the activation of FOXO3 did not fully eradicate proliferating tumor cells, but promoted heterogeneity of the residual tumor tissue with some FOXO3-negative tumor cells and NB cells with high, nuclear FOXO3 levels that apparently persisted during 4OHT-induced FOXO3 activation." (PMID 27769056, 2016). "Besides, it has been briefly suggested that autophagy modulation by regorafenib could account for its anti-tumor activity, but the potential regulatory effects of this multi-kinase inhibitor on FOXO3 and autophagy in sorafenib-resistant HCC has not been investigated yet." (PMID 34769197, 2021). "Structure-function studies identified an inactive linear isomer of ONC201 that does not affect Akt/ERK/Foxo3 signaling, and is unable to induce TRAIL and cell death in tumor cells." (PMID 27602582, 2016). "It was demonstrated in several human tumor cell lines cells that FOXO3 (but interestingly neither FOXO1 nor FOXO4) stimulates the transcription of the Keap-1 gene, regulating Keap-1 protein levels; of note, this FOXO3/Keap axis appears to exist in human but not murine cells." (PMID 28818793, 2017).
cancer (594 papers, 2010 to 2026). A tumor composed of atypical neoplastic, often pleomorphic cells that invade other tissues. "Many studies suggest that the dysregulation of FOXO3 activity is associated with the development and progression of various types of cancer in humans." (PMID 39334758, 2024). "It is becoming obvious that FOXO3 must be active to keep cells under control and that FOXO3 inactivation is linked to features of cancer cells." (PMID 37976368, 2024). "The inactivation or dysregulation of Foxo3 has been implicated in the pathogenesis of various cancers, including breast, liver, colon, prostate, bladder, and nasopharyngeal cancers." (PMID 39729481, 2024). "It is noteworthy that the FOXO3-associated signaling pathways have been recognized as therapeutic targets for various cancers, and our research findings provide a novel mechanistic understanding of SIRT1 as an upstream regulatory factor." (PMID 39266959, 2024). "The transcription factors FoxO1 and FoxO3, in particular, have been linked to the emergence and progression of a variety of cancer entities and suggested as therapeutic targets." (PMID 39766892, 2024). "Evidence supported that the aberrant expression or dysfunction of FOXO3 was associated with various types of cancers including RMS." (PMID 38720807, 2024). "As systemic Foxo3 knockdown has also been associated with risks of inflammation and cancer progression, a muscle-specific approach would be necessary." (PMID 38132107, 2023). "As an often-reviewed driver in carcinogenesis, FOXO3 is described as a tumor suppressor gene that was identified to be inactivated by mutations or posttranslational modifications in cancer." (PMID 38132107, 2023). "FOXO3 is generally considered an anti-oncogene, and its inactivation is associated with the occurrence and development of various cancers." (PMID 34795388, 2022). "The aim of this study was to assess the association of DNA methylation at the FOXO3 gene measured in peripheral blood with several age-related outcomes: cancer risk, cancer survival, and mortality." (PMID 34943892, 2021). "Conditional logistic regression was used to assess associations between cancer risk and methylation at 45 CpGs of FOXO3 included on the HumanMethylation450 assay." (PMID 34943892, 2021). "Its inactivation is, furthermore, associated with the initiation and progression of cancer: FOXO3 knockout mice show increased Ki-67 staining in colon crypts due to increased cell cycle activity, respectively." (PMID 34073605, 2021). "There is evidence supporting that FOXO3 deregulation is associated with autophagy modulation, being related to the loss or gain of drug sensitivity in different cancer types." (PMID 34769197, 2021). "Although the known functions of FOXO3 are consistent with a potential role in cancer survival, further studies are required to elucidate the underlying mechanisms that would explain different roles of FOXO3 methylation across cancer types and CpG sites." (PMID 34943892, 2021). "Several studies have found that dysregulation of FOXO3 was associated with cancer progression and poor prognosis." (PMID 34943892, 2021). "Given the vital role of Foxo3 in other cancer types, we focused on the function of Foxo3 in OC progression and the underlying mechanism." (PMID 34555810, 2021). "FOXO3 has been associated with a number of age-related diseases, including cancer, CVD, intervertebral disc (IVD) degeneration, and neurodegenerative diseases." (PMID 35004893, 2021). "For instance, inactivation of FOXO3 is associated with the initiation and progression of cancer and has a role in infectious diseases through regulation of IL-10." (PMID 35047509, 2021).
cancer (continued). "Long-lived men had homozygosity for the G-allele of FOXO3 rs2802292 and showed lower prevalence of cancer and cardiovascular diseases along with greater insulin sensitivity compared to younger controls." (PMID 31303978, 2019). "Cancers with activating Ras mutations exhibit enhanced autophagy, where FOXO3 plays a critical role." (PMID 29301589, 2018). "Specifically, tumorigenesis, cancer progression and the development of cancer therapy resistance have often been associated with FOXO3 inactivation or/and FOXM1 overexpression." (PMID 29180117, 2018). "This SNP lies in the FOXO3 gene, well‐known for its relationship with longevity, and it is possible that this is driving the association with cancer." (PMID 27225428, 2016). "For example, both showed inhibition of FOXM1 and activation of FOXO3—forkhead transcription factors with reciprocally antagonist actions implicated in many cancers and in cardiomyocyte proliferation." (PMID 26138449, 2016). "We concluded that the activation of Foxo3 is required for ergosterol peroxide-induced cancer cell death, which is strongly associated with pro-apoptotic protein Bax and Puma." (PMID 27058618, 2016). "Low levels of FOXO3 have been reported to confer chemotherapy resistance in human cancers, being significantly associated with poor prognosis in cancer patients." (PMID 26643256, 2015). "To investigate the molecular mechanism underlying miR-182-mediated cancer cell proliferation, we studied an important miR-182 target gene, FOXO3." (PMID 24519909, 2014). "However, it is thought that FOXO3 plays a role in a variety of processes that are associated with aging and cancer." (PMID 39334758, 2024). "In different cancers, the variant expression of FOXO3 has variant effects on prognosis." (PMID 38725864, 2024). "There are different examples of Foxo3 knockdown being associated with cancer progression." (PMID 38132107, 2023). "Moreover, FOXO3 acts as a tumor suppressor, and its loss of activity has been shown to be closely associated with cancer initiation and progression." (PMID 35323693, 2022). "Here, we assessed whether blood DNA methylation at FOXO3 was associated with cancer risk, survival, and mortality." (PMID 34943892, 2021). "We evaluated expression of FOXO3 mRNA in MM patient samples using publicly available gene expression profiling data because FOXO3 has been implicated in the pathogenesis of several other cancers." (PMID 33216827, 2020). "FOXO transcription factors have been implicated in a plethora of different cellular functions, in cancer immunity where loss of FOXO3 exerts anti-cancer effects, but also hampers other arms of the immune system, in neuronal development and plasticity, cancer angiogenesis and metabolism." (PMID 31789593, 2019). "However, increasing evidence demonstrates that high expression of FOXO3 is linked to a poor patient prognosis in several types of cancer." (PMID 31488102, 2019).